INS (insulin)
Diseases named in the same sentence as INS in open-access papers (continued):
Sharing a sentence is not in itself a finding about the gene and the disease.
type 1 diabetes (continued). "With insulin therapy, and in the absence of nephropathy, ATP and phosphocreatine levels at rest and post exercise appear normal in individuals with type 1 diabetes." (PMID 32533229, 2020). "The Glucose-Insulin-Glucagon nonlinear model accurately describes how the body responds to exogenously supplied insulin and glucagon in patients affected by Type I diabetes." (PMID 30893335, 2019). "Insulin replenishment is critical for patients with type 1 diabetes; however, current treatments such as pancreatic islet transplantation and insulin injection are not ideal." (PMID 30670068, 2019). "In our study we showed that the combination of an immunomodulatory agent such as the non-depleting anti-CD4 antibody with AAV-based insulin gene therapy allowed increased therapeutic benefit also for Type 1 diabetes." (PMID 30514969, 2019). "Because insulin delivered exogenously is not subject to normal physiological feedback regulation, hypoglycemia is common in patients with Type 1 diabetes who undergo treatment." (PMID 30893335, 2019). "Type 1 diabetes (T1D) is characterized by the autoimmune destruction of the pancreatic beta-cell population and the consequent decrease or lack of insulin secretion." (PMID 31266981, 2019). "For individuals with diabetes type 1 there are currently no recommendations concerning insulin adjustments and/or the CHO-intake during prolonged endurance sports when physical performance is to be considered." (PMID 31496994, 2019). "Type 1 diabetes is a type of diabetes mellitus induced by very little or no insulin produced in the pancreas." (PMID 30863376, 2019). "There are three major types of autoantibodies found in type 1 diabetes such as GDP65, IA2, and insulin autoantibodies, but antibodies against insulin can be identified mostly in young patients and may be lacking in adults." (PMID 31827713, 2019). "Type 1 diabetes (T1D) is an autoimmune condition characterized by elevated blood glucose levels due to the lack of endogenous insulin production." (PMID 31597288, 2019). "In type I diabetes, β-cells in the islets of Langerhans of the pancreas are damaged, and insulin is not secreted." (PMID 31266160, 2019). "Until now, insulin‐triggered type 1 diabetes has been reported only in Japanese individuals, but not from other countries." (PMID 30970177, 2019). "When the beta cells are destroyed or incapacitated, as happens in type 1 diabetes, insulin is no longer produced in sufficient amounts and the tissues are unable to metabolise glucose despite it being abundant in the circulation." (PMID 30514969, 2019). "Limited research in type 1 diabetes suggests that interventions with exercise programs improve lipid levels, endothelial function, and insulin resistance but not blood pressure." (PMID 31607950, 2019). "Clinicians should be aware that patients progressing to insulin within 3 years of diagnosis have a high likelihood of type 1 diabetes, regardless of initial diagnosis." (PMID 30969375, 2019). "In mouse models of type 1 diabetes, leptin is surprisingly able to reverse hyperglycemia independent of insulin therapy." (PMID 30357355, 2019). "Type 1 diabetes (T1D), also known as juvenile diabetes or insulin-dependent diabetes, is a form of diabetes in which very little or no insulin is produced by the pancreas." (PMID 31581697, 2019). "Patients with type 1 diabetes have high blood sugar, often accompanied by ketosis, nausea, vomiting and positivity for antibodies (ICA, IAA and GAD) in laboratory tests, the function of islets is poor and long-term insulin replacement is required." (PMID 31322178, 2019). "Type 1 diabetes (T1D) can be identified prior to the onset of clinical symptoms by measuring islet autoantibodies (iAb) to glutamic acid decarboxylase (GAD), insulinoma antigen 2 (IA-2), zinc transporter 8 (ZnT8), and insulin in serum." (PMID 31398795, 2019).
type 1 diabetes (continued). "However, these B cells can still present antigen and stimulate both naive and insulin-specific CD4 T cells, suggesting that even in an impaired state, autoreactive B cells can still promote type 1 diabetes." (PMID 31444529, 2019). "Our study elucidated the importance of orally administered carbohydrates to maintain euglycemia during moderate-intensity exercise when pre-exercise bolus insulin was not reduced in individuals with type 1 diabetes." (PMID 31174360, 2019). "This potential is hindered by a challenge of maintaining blood glucose within range with insulin therapy, that is especially demanding for persons with type 1 diabetes, who often do not achieve appropriate chronic glucose control." (PMID 31607950, 2019). "In our study, we followed up patients with type 1 diabetes, some of them on insulin pumps, a population not studied in previous studies held in a specialist clinic." (PMID 29998139, 2018). "In conclusion, our results show that in newly diagnosed adolescents with type 1 diabetes and deranged metabolism, the IGF-1 level is low and rapidly improves with insulin treatment but later tends to decrease concomitantly with declining endogenous insulin secretion." (PMID 29744370, 2018). "The presence of autoantibodies against the beta cells of the pancreas and the lack of endogenous insulin secretion are biologic markers of type 1 diabetes." (PMID 29596402, 2018). "For this reason, we limited the analysis to those diagnosed with type 1 diabetes under the age of 40 years, on insulin alone and with no history of oral hypoglycaemic prescriptions." (PMID 29478098, 2018). "Type I diabetes (insulin-dependent diabetes) results from the cellular mediated autoimmune destruction of pancreatic islet cells leading to absence of insulin." (PMID 29868580, 2018). "The precise role of autoantibodies against β cell autoantigens, such as insulin-specific autoantibodies, glutamic acid decarboxylase, insulinoma antigen, and zinc transporter-8, in the pathogenesis of type 1 diabetes is unclear but of great significance to the prediction and diagnosis of T1DM." (PMID 30345316, 2018). "While cognisant of the complete or near-complete destruction of ß-cells in type 1 diabetes, we nevertheless postulated that SIRT1 may still exert its energy conserving effects in this setting but would need to do so through insulin-independent mechanisms." (PMID 30228292, 2018). "Diabetes (high blood sugar) has long been recognized to be a heterogeneous disease, but, originally, even insulin-dependent and non-insulin dependent diabetes were not differentiated." (PMID 29444168, 2018). "The pursuit of strict glycaemic control with analogue insulin has not fully realised the anticipated improved rates of hypoglycaemia in type 1 diabetes." (PMID 29273897, 2018). "Furthermore, CYM5443 also limits the migration of autoimmune cells to pancreatic islets in a mouse model of type 1 diabetes (Rip-LCMV T1D model), preserving insulin production and maintaining glucose regulation." (PMID 29608575, 2018). "This is very important for type 1 diabetes, where there is not an endogenous production of insulin from the pancreas." (PMID 32232085, 2018). "Randomised controlled trials in non-pregnant outpatients with type 1 diabetes that compared the use of any artificial pancreas system with any type of insulin based treatment." (PMID 29669716, 2018). "Insulin seems to be actively transported into milk irrespective of the source because exogenous insulin used for treatment of type 1 diabetes is found in human milk." (PMID 30519550, 2018). "We retrospectively analysed data from 60 adults with type 1 diabetes who received, in a crossover randomized design, day‐and‐night hybrid closed‐loop insulin delivery and insulin pump therapy, the latter with or without real‐time continuous glucose monitoring." (PMID 29577536, 2018).
type 1 diabetes (continued). "This has been previously observed in subjects with type 1 diabetes where infused insulin did not suppress α-cell production of glucagon, but also in subjects that had tight glycaemic control." (PMID 29494594, 2018). "A previous study highlighted similar findings where non-metabolic secretagogues elicit insulin release in prediabetic conditions and in type 1 diabetes." (PMID 29209740, 2018). "Virtually all patients with type 1 diabetes require insulin to survive, and very few persons who use insulin do not report using it." (PMID 29596402, 2018). "To date, there is no apparent cure for diabetes mellitus type I, and therefore those with type I diabetes need to take insulin for life to control blood glucose levels." (PMID 30366359, 2018). "Conversely, in T2D (formerly called adult-onset or non-insulin-dependent diabetes) the body is not able to use insulin appropriately; this is referred to as the phenomenon of insulin resistance." (PMID 29534427, 2018). "In conclusion, our results show that in newly diagnosed adolescents with type 1 diabetes and deranged metabolism, IGF-1 levels are low and rapidly improving with insulin treatment but later tend to decrease concomitantly with declining endogenous insulin secretion." (PMID 29744370, 2018). "There is no alternative to Insulin for Type-1 diabetes and Type-2 diabetics will also need insulin after few years." (PMID 30344599, 2018). "Our findings may not accurately represent patients with type 1 diabetes in the general population because all our patients were veterans seen at the VA and most had insulin pumps, which are associated with better glycemic control compared with insulin injections." (PMID 29369757, 2018). "NOD (non-obese diabetic) mice spontaneously develop type I diabetes (T1D) as a result of the autoreactive destruction of the insulin-producing β cells in the pancreatic islets." (PMID 29757216, 2018). "Phase 5 would characterize the time at which the individual has complete failure of pancreatic beta cells, leading to type 1 diabetes, with total absence of insulin and blood ketosis in the individual." (PMID 29924854, 2018). "Six HIV-infected participants were treated with blood pressure-lowering drugs, two with lipid-lowering drugs, and one with insulin for type 1 diabetes, whereas no participant in the ENNS survey received any of these drugs." (PMID 30408056, 2018). "Type-1 diabetes is a chronic condition that is characterized by an excessive increase in blood glucose level because the pancreas does not produce insulin hormone due to the autoimmune destruction of pancreatic beta cells." (PMID 30693047, 2018). "In addition, OA has also been reported to work synergistically with insulin therapy in lowering blood glucose as well as ameliorating renal and hepatic dysfunction in STZ-induced type 1 diabetic rats." (PMID 29596390, 2018). "Nevertheless, metformin has been shown to reduce insulin dose requirement without improving glycemic control such as with glucose concentration, as well as HbA1c in type 1 diabetes." (PMID 29338714, 2018). "Type 1 diabetes (T1D) is an autoimmune disease that develops as a consequence of β-cell death and subsequent lack of insulin." (PMID 30687329, 2018). "Fourth, we did not assess the effects of treatment drugs (human insulin, insulin analogues) on the outcomes of pregnant women with type 1 diabetes." (PMID 29113335, 2017). "The most common type of DM is type 1 diabetes (T1DM) in which insulin is lacking as a result of failure of the pancreas." (PMID 29096704, 2017). "Patients with type 1 diabetes exhibit pancreatic β cell damage, resulting in a lack of insulin and ketoacidosis." (PMID 28758131, 2017). "Insulin users (47% type 1 diabetes women) were more often premenopausal compared to non-insulin users (p = 0.04); and insulin users with premenopausal breast cancer had lower BMI compared to those not treated with insulin (p = 0.0003)." (PMID 28076434, 2017).
type 1 diabetes (continued). "We observed a negative correlation between insulin sensitivity and BMI in agreement with previously reported data in adults with type 1 diabetes." (PMID 28371223, 2017). "The consensus conclusion from the total body of work is that complete lack of insulin, as in severe long-standing type 1 diabetes, locks the liver in a state where blunting of glucagon action is unable to downregulate glucose production." (PMID 28323959, 2017). "Further studies are needed to clarify the clinical consequences of a lack of insulin in the liver for patients with type 1 diabetes." (PMID 28192442, 2017). "Further studies are needed to understand the clinical consequences of a lack of insulin in the liver in patients with type 1 diabetes." (PMID 28192442, 2017). "Adults with type 1 diabetes can engage in HIIT and manage blood glucose with appropriate regimen changes, which may include more insulin during and following and activity and reduced dosing overnight, along with food intake to prevent overnight hypoglycemia." (PMID 28265261, 2017). "This proposal caused considerable debate, particularly regarding the pathophysiology of type 1 diabetes; the existing dogma—that the clinical features of the disease were entirely due to lack of insulin—was not easily abandoned." (PMID 28323959, 2017). "Our results suggest that MSCs grown in high-glucose media for 11–13 passages exhibit the characteristics of precursors to insulin-producing cells and, when administered to NOD mice before the clinical onset of symptoms, help in preventing type 1 diabetes-like symptoms in the mice." (PMID 28701182, 2017). "This is, to our knowledge, the first randomised controlled study that investigates the efficacy of closed-loop insulin delivery with unannounced physical activity and without uncovered snacks in a juvenile population with type 1 diabetes." (PMID 28840263, 2017). "MBL concentration decreased following the initiation of insulin pump therapy in patients with type 1 diabetes and did not correlate with changes in glycaemic control." (PMID 29318157, 2017). "Type 1 diabetes (T1D) is a T-helper 1- (Th1-) mediated autoimmune disease that is characterized by a lack of insulin due to autoimmune destruction of pancreatic beta cells." (PMID 28553653, 2017). "We conclude that lack of insulin in the liver contributes to the changes in fat metabolism observed in type 1 diabetes." (PMID 28192442, 2017). "It has been unclear whether aberrations of fat metabolism in type 1 diabetes are caused by the absence of insulin in the liver, by decreased fatty acid substrate availability in the blood secondary to peripheral hyperinsulinemia due to subcutaneous insulin injections, or by a combination of both." (PMID 28192442, 2017). "In contrast to participants with Type 1 diabetes in the study of Anderbro participants in our study did not use insulin at baseline." (PMID 27537359, 2016). "First phase insulin response (FPIR), calculated as the sum of serum insulin concentrations at 1 and 3 min in the IVGTT, has been shown to decline before the diagnosis and a reduced FPIR clearly predicts clinical type 1 diabetes." (PMID 26620391, 2016). "Type 1 diabetes (T1D) is a spontaneous organ-specific autoimmune disease, and a series of autoantigens have been identified in both humans and NOD mice, including insulin and glutamic acid decarboxylase (GAD)." (PMID 26783749, 2016). "As a matter of fact, all individuals with Type 1 diabetes should receive insulin, and it is quite impossible to do so in Italy without having been visited and having received a prescription by a paediatrician or a general practitioner." (PMID 27092312, 2016). "Absorbed glucose has a varying ability to stimulate pancreatic insulin secretion across individuals, with type 1 diabetes being an extreme case in which insulin is only minimally secreted or not at all." (PMID 27253712, 2016).
type 1 diabetes (continued). "In type-1 diabetes, the beta cells are destroyed due to an autoimmune response and there is no insulin production." (PMID 27916864, 2016). "This case highlights complex physiological interplay between type-1 diabetes, noncompliance to insulin, and cocaine abuse leading to DKA, with starvation physiology causing development of euglycemic DKA." (PMID 27579186, 2016). "Many diabetic patients are not able to produce insulin and rely on regular insulin injections to prevent their blood glucose from reaching dangerous levels (insulin-dependent diabetes)." (PMID 27190125, 2016). "The incidence rates for adjudicated MACE+ or MACE by individual study or patient group were not statistically different between BIL and comparator insulin treatment, except for patients with type 1 diabetes." (PMID 27188479, 2016). "As another example, mice with STZ-induced type 1 diabetes do not show impaired cardiac efficiency, unless cardiomyocyte insulin resistance, a feature of type 2 diabetic hearts, is induced by deletion of cardiomyocyte insulin receptors." (PMID 27999359, 2016). "Our findings are consistent with recent studies where EXE and Lira administration reduced fasting and postprandial blood glucose levels, and improved insulin sensitivity, in subjects with type 1 diabetes with absent endogenous insulin secretion." (PMID 27473212, 2016). "Insulin is a natural vital treatment in type 1 diabetes, because of the total absence of insulin secretion." (PMID 27391319, 2016). "When there is no local insulin production in type 1 diabetes, pancreas volume is known to be decreased by one third and this is evident from just after diagnosis." (PMID 27179658, 2016). "The existing standard therapy for patients with insulin-dependent diabetes (type 1) and advanced patients with non-insulin-dependent diabetes (type 2) diabetics includes everyday insulin injections, and frequent fingerstick calibrations to monitor BGLs." (PMID 27792179, 2016). "For many years, type 1 diabetes (T1D) was defined as an autoimmune disease in which autoreactive T cells escape negative selection and destroy the insulin-producing beta cells." (PMID 26918165, 2016). "Data from a Spanish group of individuals with type 1 diabetes and aged on average 17 years old showed that insulin dose per body surface but not with dose per kg of body weight was higher in individuals with metabolic syndrome." (PMID 27011769, 2016). "We had a very low proportion of patients with type 1 diabetes and the lack of information on insulin use likely underestimated the sample size for that predictor and reduced our power." (PMID 25780626, 2015). "Type 1 diabetes is suggested by the presence of circulating, islet-specific, pancreatic autoantibodies against glutamic acid decarboxylase (GAD65), the 40K fragment of tyrosine phosphatase (IA2), insulin, and/or zinc transporter 8 (ZnT8)." (PMID 25621692, 2015). "Strowig and Raskin reported improved glycemic control without an increase in insulin demand in 25 overweight adult patients with type 1 diabetes following therapy with 4 mg rosiglitazone twice a day for 8 months." (PMID 26273677, 2015). "They classified patients <30-years old using insulin monotherapy and never using oral antidiabetes medications as having type 1 diabetes." (PMID 26048371, 2015). "They concluded that insulin antibodies do not develop during pregnancy with the use of aspart in type 1 diabetes and that 1-5 % of human insulin concentration was transferred to the fetal circulation." (PMID 27057336, 2015). "Type 1 diabetes is due to an autoimmune destruction of the insulin-producing pancreatic β-cells leading to the lack of insulin production." (PMID 26576302, 2015). "The effects of basal-bolus insulin therapy for 4 weeks with either IDeg or IGlar as the basal insulin in adult C-peptide-negative outpatients with type 1 diabetes were investigated in an open-label, multicentre, randomised, crossover trial." (PMID 26044206, 2015).